OR4F4 (olfactory receptor family 4 subfamily F member 4)
Description:
Odorant receptor.
Synonyms: OR4F18; OLA-7501
Gene: Protein-coding gene on chromosome 15 (101,922,042 to 101,923,113, reverse strand). Ensembl gene ENSG00000177693.
Subcellular location: Cell membrane
Pathways (Reactome):
Sensory Perception: Expression and translocation of olfactory receptors
Genetic constraint (gnomAD): Loss-of-function variants: 1 observed, 2.73 expected, observed/expected ratio (o/e) 0.37, 90% interval 0.13 to 1.55. That is too few expected variants to judge how well the gene tolerates losing a copy. Missense variants: 7 observed, 60.19 expected, observed/expected ratio (o/e) 0.12, 90% interval 0.065 to 0.22. Synonymous variants: 1 observed, 22.3 expected, observed/expected ratio (o/e) 0.0448, 90% interval 0.015 to 0.21.
Homologues: Orthologues: rat Or4f4b (81% identical), mouse Or4f4-ps1 (80% identical), mouse Or4f4b (80% identical), mouse Or4f17 (79% identical). Paralogues in human: OR4F5 (99% identical), OR4F17 (93% identical), OR4K1 (57% identical), OR4F6 (56% identical), OR4F15 (56% identical), OR4K15 (55% identical), OR4F16 (55% identical), OR4F21 (55% identical), OR4F29 (55% identical), OR4F3 (55% identical), OR4K17 (54% identical), OR4K13 (54% identical), and 116 more.
Diseases named in the same sentence as OR4F4 in open-access papers:
OR4F4 is named in the same sentence as 1 disease in open-access papers, as found by Europe PMC text mining. Sharing a sentence is not in itself a finding about the gene and the disease.
OR4F4 shares sentences with these, for which no sentence is quoted: viral infection (1 paper).